IL6 (interleukin 6)
Diseases named in the same sentence as IL6 in open-access papers (continued):
Sharing a sentence is not in itself a finding about the gene and the disease.
cancer (continued). "Moreover, STAT3 phosphorylation by EGF or IL-6 was diminished in multiple CARP-1 null cancer cells." (PMID 42121855, 2026). "Furthermore, IL-6 is associated with an aggressive PC phenotype and may facilitate metastasis by regulating EMT and the invasion of cancer cells into the bone." (PMID 41596531, 2026). "Although the hematological results suggest an increase in WBC, which could indicate systemic inflammation, the lack of elevated levels of albumin, CRP, and IL-6 suggests that cancer did not cause systemic inflammation." (PMID 40284805, 2025). "A research has revealed that when FAM50A was knocked down, it could lead to DNA damage, elicit the expression of interferon beta and interleukin-6, and inhibit the proliferation, invasion and migration of cancer cells, which is basically in accordance with our results in this study." (PMID 39999107, 2025). "Given that cancer cells utilize multiple pathways to evade immune elimination and extensive cross-interactions among these pathways, combinational therapy against PD-L1, Tbsax1, and/or IL-6 may offer better therapeutic outcome." (PMID 39996058, 2025). "However, while low IL-6 levels facilitate SC activation and muscle fiber regeneration, persistently high IL-6 levels contribute to skeletal muscle atrophy, which may partly explain the muscle wasting seen in cancer." (PMID 40104495, 2025). "While suppressing cytokines like IL-6 and TNF-α can be beneficial, over-suppression may lead to immunosuppression and increased susceptibility to infections, thus complicating treatment in cancer patients." (PMID 40544399, 2025). "Moreover, RT may mitigate treatment-induced elevations in IL-6, thereby alleviating cancer-related fatigue and pain." (PMID 40895542, 2025). "Additionally, it reduces IL-6 production in C26 cancer cells." (PMID 41011274, 2025). "Thus, IL-6 serves as a key player in suppressing CD8+ T cells—either indirectly through the differentiation of suppressive TAMs or directly—ultimately undermining cancer immunity." (PMID 39652104, 2025). "Of key importance, IL-6-specific ELISPOTs were undetectable in our co-culture experiments across all tested cancer cell lines and tissues, suggesting that IL-6 production may not play a significant role in the interaction between γδ T cells and cancer cells under the conditions tested." (PMID 40801630, 2025). "In humans, a recent cross-sectional observational study enrolling 624 adults in the American Cancer Society’s Cancer Prevention Study-3 Diet Assessment Substudy found a positive association between the consumption of artificial NNSs, including ASP, SAC, SUC, and Ace-K, and leptin, CRP, and IL-6." (PMID 41156503, 2025). "However, since IL-6 and CCL2 have different receptors, the signaling pathways associated with the differences in ligand expression on the active receptors on the cancer cell surface may have been different." (PMID 40430040, 2025). "Additionally, cancer cachexia is associated with decreases in serum albumin, triglycerides (TG), cholesterol, high-density lipoprotein (HDL), and low-density lipoprotein (LDL) and increases in pro-inflammatory cytokines such as IL-6, IL-1β, and TNF-α." (PMID 40469669, 2025). "Furthermore, IL-6 plays a key role in tumorigenesis, cancer progression, and treatment resistance." (PMID 39796190, 2025). "However, the potential therapeutic effects of blocking IL-6 combination with ICIs are unknown in cancer patients." (PMID 40255422, 2025). "Interleukin-6 (IL-6) is a key immunomodulatory cytokine involved in distinct physiological and pathophysiological functions, ranging from cell development and differentiation to inflammation and cancer, being heavily synthesized in the body during infections and inflammatory processes." (PMID 38980514, 2025). "Moreover, inhibiting IL-6 signaling significantly reduced the growth rate of cancer cells." (PMID 40839565, 2025).
cancer (continued). "Transcriptomic and pathway analyses revealed that cancer-exposed monocytes adopt a reprogrammed phenotype marked by activation of pro-tumorigenic signaling pathways, enhanced proliferative capacity, and elevated expression of pro-inflammatory cytokines such as IL6." (PMID 41514627, 2025). "Moreover, the expression levels of IL-6 and IL-1β were significantly elevated in the cancer group." (PMID 41267807, 2025). "Interestingly, IL-6 has also been implicated in wound healing and SASP, demonstrating that multiple factors associated with SASP are likely capable of driving acquisition of both the wound healing and stem cell signatures in cancer." (PMID 41497628, 2025). "Besides other well-established risk factors such as female sex and dual ICI therapy, low rather than high post-ICI IL-6 levels were associated with irAE occurrence in a pan-cancer cohort of patients treated with ICIs." (PMID 41019062, 2025). "Therefore, given its involvement in inflammation and cancer progression, IL-6 could serve as a potential target for therapeutic interventions in CC." (PMID 41561529, 2025). "Thus, IL-6-targeted therapies that inhibit STAT3 activity could still be effective against cancer cells chronically exposed to IL-1." (PMID 41374981, 2025). "The identification of miR-21 as a direct transcriptional target of STAT3 firmly places it within the inflammation-cancer axis, suggesting that the pro-tumorigenic effects of chronic inflammation (e.g., mediated by IL-6) in the stomach may be, at least in part, channeled through miR-21 upregulation." (PMID 41476448, 2025). "Low H2O2 levels can trigger NF-κB, an oxidative stress detector; this can trigger the production of anti-apoptotic genes and pro-cancer cytokines like interleukin-6 (IL-6) and tumor necrosis factor alpha (TNF-α) and may activate or suppress MAPK phosphorylation." (PMID 40732979, 2025). "IL-6, IL-8, monocyte chemoattractant protein-1 (MCP-1), tissue inhibitor of metaloproteinase-1 (TIMP-1) and adiponectin released by adipocytes are associated with the ovarian cancer cells homing in the omentum and are considered as factors responsible for recruiting of cancer cells to the omentum." (PMID 40136652, 2025). "For instance, interleukin (IL) 6 (IL-6), transforming growth factor beta (TGF-β), fibroblast growth factor 2 (FGF2), monocyte chemoattractant protein 1 (MCP-1), and vascular endothelial growth factor A (VEGFA) have been linked to the pre-cancer or initiation (formation) of HCC." (PMID 41219858, 2025). "In addition, higher TNF-α and IL-6 expression was observed in the Cat D KO cancer cells." (PMID 38297161, 2024). "Additionally, IL-6 signaling may also play a role in promoting the growth, invasion, and spread of different cancer types." (PMID 38891090, 2024). "Therefore, IL6 trans-presentation by dendritic cells plays a vital role in shaping immune responses, balancing inflammation, and influencing the progression of diseases like cancer." (PMID 39766086, 2024). "Thus, in cancer, various cytokines, including IL-6 and CCL5, are secreted into the TME at various stages of inflammation, and their complex interactions and secretions may be altered." (PMID 39126553, 2024). "While the similarity of the cytokines secreted by the MSCs and cancer cells is surprising, these increase in the secretion of two inflammatory cytokine, IL-6 and CCL2, suggests that even 120 h co-culturing with cancer cells could lead MSCs to establish a pro-inflammatory microenvironment." (PMID 38674102, 2024). "Moreover, previous studies have highlighted the role of IL-6 in cancer prognosis." (PMID 39697224, 2024). "Unlike for irAEs, IL-6 significantly dichotomized patients at increased risk for cancer-specific and all-cause mortality at a much higher optimal cutoff of 2.3 fold change (P < 0.001), revealing that the subset of patients with the highest increase in IL-6 was at a disparate risk of early death." (PMID 39403935, 2024).
cancer (continued). "Tocilizumab, an IL-6 receptor antagonist, and Siltuximab, an anti-IL-6 antibody, have been shown to inhibit IL-6 signaling; they were initially studied for treating cytokine release syndrome, and clinical and preclinical studies are now underway to evaluate their efficacy in a variety of cancers." (PMID 39421736, 2024). "Chia ether significantly minified IL-6 (75.20 ± 0.96 ng/mL) and IL-1β (59.98 ± 2.16 pg/mL) levels more than chia alcohol (80.73 ± 0.73 ng/mL and 61.35 ± 1.63 pg/mL, respectively), compared to the cancer lung control, 67.10 ± 1.72 ng/mL and 69.08 ± 0.83 pg/mL, respectively." (PMID 39338293, 2024). "There are increasing indications of a link between inflammation and the development of cancer where invasion-promoting factors (matrix metalloproteinases (MMPs) 2 and 9) and nuclear factor kappa B (NFκB)-dependent proinflammatory cytokine interleukin 6 (IL-6) support the malignant phenotype." (PMID 39337548, 2024). "A central role for IL-6 in promoting peritoneal carcinomatosis has been inferred from research consistently demonstrating elevated levels of IL-6 in the serum and ascites of patients with PC compared to those without it, in ovarian, colorectal, gastric and other cancers." (PMID 38689325, 2024). "Moreover, in the BM of MM patients, cancer cells stimulate the secretion of IL-1β and IL-6." (PMID 38610941, 2024). "Targeting the IL-6/JAK2/STAT3 signaling axis may enhance the effectiveness of cancer therapies." (PMID 39103836, 2024). "Mechanistically, cancer cells capable of inducing cancer cachexia are secreting IL-6, which subsequently induces autophagy in differentiated muscle cells via IL-6 signaling and therefore might be relevant for the characteristic muscle and weight loss during cancer cachexia." (PMID 38660307, 2024). "We observed differential mRNA expression of growth factors and cytokines (TGFβ, IL-6, and IGF1) both in BMSCs and, subsequently, in cancer-associated fibroblasts (CAFs), which might represent the main cell subpopulation responsible for inflammatory homeostasis in MM, among the two patient subgroups." (PMID 39609411, 2024). "Additionally, IL-6 might also alleviate cancer-related fatigue, potentially via the actions of pro-inflammatory cytokines IL-1β and TNF-α." (PMID 39346906, 2024). "The association between IL6 and stress-related hormones, such as adrenocorticotropic hormone (ACTH) and cortisol, could potentially explain the differences in IL6 levels between cancer and control patients." (PMID 38339282, 2024). "Therefore, based on our studies, a hypothesis has emerged that calcitriol-stimulated 4T1 cells, by secreting PGE2, induce TAMs M2 polarization and IL-6 production, and this cytokine, in turn, promotes the invasive potential of cancer cells." (PMID 38355711, 2024). "The decrease in their proliferation potential may be attributed to the secretion of several inflammatory molecules, such as IL-1β, IL-6, IL-8, IL-10, and matrix metallo-proteinases (MMPs) by cancer cells, which have adverse effects on the neighboring cells in the niche." (PMID 39768220, 2024). "Our study revealed that elevated serum IL-6, TNF-α, and TGF-β and decreased IL-10 levels revealed that patients with ESCC and model mice demonstrated increased immune levels, and these inflammatory cytokines are considered important mediators associated with inflammation and cancer." (PMID 38834834, 2024). "Interleukin 6 (IL-6) derived from skeletal muscles has been identified as the first myokine secreted into the systemic circulation Subsequent clinical and experimental studies have demonstrated its pleiotropic activity and its multifaceted role in cancer cachexia." (PMID 39411315, 2024). "In addition, an increase in IL-6, TGFβ, and lactate secretion after prolonged co-culture indicated a small part of the fact that intracellular communications between cancer cells and fibroblasts play a key role in promoting the normal fibroblasts to acquire new secretion phenotypes." (PMID 38361760, 2024).
cancer (continued). "Indeed, cancer associated fibroblasts were shown to induce de-differentiation of non-CSCs to CSCs via IL-6 signaling." (PMID 38765006, 2024). "Interestingly, the association between IL-6 and EMT has been observed in various cancers." (PMID 39683528, 2024). "It has been suggested that various inflammatory cytokines and chemokines, such as IL-6 and IL-8, not only promote cancer cell proliferation and activation but may also synergistically promote cancer progression through the suppression of natural killer cell function." (PMID 38999874, 2024). "Therefore, a potential therapeutic approach for cancer treatment could involve suppressing IL-6 or its signalling pathway alone or in conjunction with conventional anticancer strategies." (PMID 39610815, 2024). "Interestingly, we also found that IL6Rα expression was negatively correlated with pSTAT3 response to IL-10, indicating that heightened IL6Rα and IL-6 in cancer patients may be dominating STAT3 signaling and in turn suppressing the IL-10 responsiveness." (PMID 39389979, 2024). "It is suggested that the secretion of pro-inflammatory cytokines IL-1, IL-6, IL-8, IL-10, TGF-β, and chemokines C-X-C chemokine ligand (CXCL)-1 and CXCL-2 by CAFs could promote monocyte recruitment and the differentiation of cancer-associated macrophages from M1 to M2." (PMID 39680287, 2024). "Thus, targeting IL‐6 production in TAMs may offer patients with cancer alternative and novel treatment options." (PMID 37974543, 2024). "This suggests that IL6 may play a role in telomere length dynamics and further cancer progression." (PMID 39766086, 2024). "Interleukin 6 (IL6), a pleiotropic cytokine, which is an important player in several cellular processes such as proliferation, immune regulation, inflammation, and invasion, has been shown to be upregulated in various cancer types and also predicts poor clinical outcomes in patients with HNSCC." (PMID 38706595, 2024). "Moreover, IL-6 impedes chemotherapy-induced anti-cancer immune responses." (PMID 36672405, 2023). "Hence, IL-6 could be a cancer progression inducer upregulated by hypoxia since the activation of this signaling pathway in hypoxic conditions by HIF-1α is associated with several steps of the metastatic cascade in which the MMPs are involved." (PMID 38069210, 2023). "We hypothesized that IL-6 expression levels can predict the clinical outcome of cancer patients." (PMID 37696858, 2023). "Furthermore, recent studies indicate that TNF-α and IL-6 promote cancer cachexia in different types of cancer, including gastric and CRC, by protein 16 containing PR domain (PRDM16) gene overexpression via the STAT3 signaling pathway, which induces the browning of WAT." (PMID 37760840, 2023). "While the role of IL-6 in cancer development has primarily been hypothesized as paracrine in nature, providing crosstalk between CAFs and cancer cells, it is possible that it may also have an autocrine function in the CAFs themselves to alter their ECM remodeling capacity." (PMID 37660739, 2023). "In addition to metabolic pathways, GLUT5 is also associated with the cancer-promotinginflammatory environment, as a positive correlation between GLUT5 expression levels and theinflammatory factor interleukin-6 (IL-6) has been observed during the progression ofmultiple cancers." (PMID 37674366, 2023). "Using single-cell transcriptomics analysis, we confirmed that the source of IL-6 and G-CSF was indeed fibroblasts/CAFs and fibrocytes, in agreement with our in vitro data and previous findings showing stromal IL-6 plays a role in invoking cancer cell proliferation." (PMID 37699010, 2023). "Therefore, the cooperated actions by these cytokines (IFN/IL-6/IL-4) on TAMs might represent a common theme in some human cancers." (PMID 36726024, 2023).
cancer (continued). "Interestingly, in COV/CA vs COV we consistently noticed upregulation of IFN-γ and downregulation of IL-6 expression levels, further supporting a regulatory effect of cancer on the activation state of circulating leukocyte populations induced by SARS-CoV-2 infection." (PMID 37063865, 2023). "Moreover, fibroblasts cultured with exosomes derived from OS cells exhibited elevated expression of pro-inflammatory genes, including IL-1β, IL-6, and IL-8, which significantly influence the regulation of the inflammatory microenvironment and the advancement of cancer." (PMID 37990331, 2023). "Therefore, the GAL reduction effect on IL-6 may be involved in controlling depressive symptoms in cancer survivors." (PMID 37371449, 2023). "In addition, IL-6 also induces epigenetic changes to contribute to the stemness of cancer cells." (PMID 37808081, 2023). "Finally, we evaluated the expression of hub genes with the development of one of the main complications of IPF patients, LUAD and LUSC, and observed that six of them (CDH2, SPP1, TNC, CYR61, SERPINA1, and IL6) were correlated with the progression of different cancer stages." (PMID 37887075, 2023). "Interestingly, using either blocking IL-6/IL-6R signaling or PD-1/PDL1 inhibitors may serve as a therapeutic target for sensitizing cancer cells to CAR-T cell treatment and restoring BCA cells to Dox treatment." (PMID 37480115, 2023). "Therefore, the method of blocking IL-6 alone or in combination with traditional cancer therapy may be a potential therapeutic strategy for the cancer where IL-6 signaling is dominant." (PMID 36845384, 2023). "Cancers cells can reprogram adipocyte physiology leading to an “activated” phenotype characterized by delipidation and secretion of inflammatory adipokines such as IL-6, leptin and fatty acids which are able to change cancer cell metabolism and signalling pathways to promote tumour progression." (PMID 36790524, 2023). "Moreover, we confirm that IL-6 hampers the effectiveness of genotoxic anticancer agents by mitigating DNA damage, driving the expression of anti-apoptotic Bcl-2 family genes, and maintaining the migratory and invasive properties of cancer cells." (PMID 37696858, 2023). "Anti-IL-6 Ab, such as siltuximab, and anti-IL-6R Ab, such as tocilizumab, have been reported to inhibit both classical signaling and trans-signaling, and their effects have been investigated in various cancer types in preclinical and early-stage clinical studies." (PMID 38469154, 2023). "In addition to mediating bone loss, IL-6 is considered a negative prognostic marker in many types of cancer and has been found to promote malignant cell proliferation, metastasis and anti-apoptotic pathways, therefore favoring disease progression." (PMID 36743421, 2023). "Therefore, the expression of IL‐6 can be enhanced in the process of malignant tumor progression." (PMID 37904699, 2023).